MAPT (microtubule associated protein tau)
Diseases named in the same sentence as MAPT in open-access papers (continued):
Sharing a sentence is not in itself a finding about the gene and the disease.
schizophrenia (9 papers, 2016 to 2026). A major psychotic disorder characterized by abnormalities in the perception or expression of reality. "Representative associations were observed for SPPL2C, MAPT, LRRC37A2, and ARL17A, whose expression in the brain was significantly associated with schizophrenia as well as with MD and λ1 of the right inferior cerebellar peduncle (ICP)." (PMID 41522603, 2026). "In particular, the expression of SPPL2C, MAPT, LRRC37A2, and ARL17A was significantly associated with schizophrenia as well as with MD and λ1 of the right ICP." (PMID 41522603, 2026). "The higher methylation reported for MAPT and NRXN1 after THC consumption was also interpreted as possibly disadvantageous in schizophrenia, as higher methylation generally leads to reduced readability of genes, which might further impair reduced synaptic connections." (PMID 35859599, 2022).
dementia with Lewy Bodies (8 papers, 2015 to 2025). "MAPT is characterized by two main haplotypes, termed H1 and H2; a previous study has indicated the role of H1G in susceptibility to dementia with Lewy Bodies." (PMID 35729600, 2022). "The relationship between MAPT haplotype and Tau and/or α-synuclein pathologies has also been investigated by studying brains affected by AD or α-synucleinopathies, including PD and dementia with Lewy Bodies (LBs)." (PMID 26170022, 2015). "Additionally, correlations between MAPT haplotypes and Lewy body dementia have been documented." (PMID 41185066, 2025).
clear cell renal cell cancer (7 papers, 2017 to 2025). "Low expression of MAPT has been linked to poor prognosis in prostate and clear cell renal cell cancer." (PMID 36110953, 2022). "Related research has shown that knocking down MAPT can promote the proliferation and invasion of renal clear cell carcinoma." (PMID 35441059, 2022). "Moreover, downregulation of MAPT was observed in 786-O clear cell renal cell carcinoma cells under long-term hypoxia." (PMID 40836964, 2025).
corticobasal syndrome (7 papers, 2013 to 2025). Corticobasal syndrome (CBS) is a rare neurodegenerative disease characterized by multifaceted motor system dysfunctions and cognitive defects such as asymmetric rigidity, bradykinesia, limb apraxia, and visuospatial dysfunction. "Tau pathology is the major neuropathological feature of “primary” tauopathies such as microtubule‐associated protein tau (MAPT)‐related frontotemporal dementia (MAPT‐FTD), progressive supranuclear palsy (PSP), corticobasal syndrome (CBS), and Pick's disease." (PMID 40437880, 2025).
diabetes (7 papers, 2012 to 2024). "Both types of diabetes are associated with central changes in the insulin/PI3K/Akt pathway that alter the phosphorylation of glycogen synthase kinase-3β (GSK3β) to promote excess phosphorylation of the microtubule-associated protein tau." (PMID 38416718, 2024). "Tobacco smoking and diabetes, both of which are associated with hypoxia, have also been shown to be associated with substantial changes in the transcription of AD associated genes, for example, APP and MAPT." (PMID 35852137, 2022). "Interestingly, it has been recently reported that abnormally hyperphosphorylated MAPT was found in pancreatic islets of individuals suffering from diabetes mellitus type 2." (PMID 26824039, 2016). "In line with the notion of MAPT expression in non-CNS tissue including the pancreas, an analogy between AD and type 2 diabetes mellitus (T2DM) has been suggested, in particular with respect to insulin signaling pathway dysfunction, protein aggregation, and oxidative events." (PMID 26824039, 2016).
gastric cancer (7 papers, 2016 to 2021). A primary or metastatic malignant neoplasm involving the stomach. "MAPT can also determine paclitaxel chemosensitivity by interacting with several miRNAs in gastric cancer and non-small cell lung cancer." (PMID 34406386, 2021). "As for the MAPT gene, miR-34c have been shown to directly regulate MAPT phosphorylation and expression yet this was only shown in gastric cancer." (PMID 29163029, 2017). "Currently, it is only known that the expression of MAPT has been correlated with drug resistance in breast and gastric cancer." (PMID 29215599, 2017). "Over expression of miR-34c significantly down-regulated MAPT protein expression and increased the chemo sensitivity of paclitaxel-resistant gastric cancer cells." (PMID 26975503, 2016). "Since higher levels of MAPT together with β-tubulin correlate with paclitaxel resistance in gastric cancer, we sought to determine if HE4 affects β-tubulin levels and microtubule stability." (PMID 27184254, 2016). "For instance, miR-34c-5p, which was found to be significantly down-regulated in PTX-resistant gastric cancer tissues, could sensitize SGC7901/VCR resistant cells to PTX via targeting and suppressing microtubule-associated protein tau (MAPT)." (PMID 32192494, 2020).
memory impairment (7 papers, 2015 to 2025). "Memory impairment has previously been described as a prominent symptom in patients with a MAPT mutation, possibly due to anteromedial temporal lobe atrophy that is often seen in MAPT." (PMID 32052166, 2020). "While memory impairment showed low statistical significance in relation to MAPT CNV mutations in exons 8 and 9, these findings may potentially correlate with memory decline in a larger sample or with more sensitive memory assessments." (PMID 40725212, 2025). "Since accumulation of microtubule-associated protein tau within hippocampal neurons is related to multiple functional impairments, these findings further confirmed the protective effects of these compounds against memory impairment." (PMID 35455468, 2022). "By these aged KA-activated APP23/MAPT mice, we demonstrated that chronic administration of LEV (L) before training partially reversed memory impairment in aged APP23/MAPT mice." (PMID 36092803, 2022).
motor neuron disease (7 papers, 2014 to 2026). "Among its clinical variants, the behavioral variant (bvFTD) is the most frequently inherited, often associated with mutations in MAPT, GRN, and C9ORF72, the latter being the most prevalent genetic cause of FTD and FTD-motor neuron disease (FTD-MND)." (PMID 41500252, 2026). "SG component proteins with a causal role for motor neuron diseases include TDP-43 (gene symbol TARDBP), FUS, ATXN2, SMN, Tau (gene symbol MAPT), HNRNPA2B1, and HNRNPA1." (PMID 24659297, 2014). "Although 21.7% of c9orf72 pathogenic variant carriers with a predominant mixed/ALS-MP had confirmed motor neuron disease, in none of the patients with a GRN or MAPT pathogenic variant, motor neuron disease was diagnosed." (PMID 35948443, 2022).
Stroke (7 papers, 2017 to 2022). Sudden impairment of blood flow to a part of the brain due to occlusion or rupture of an artery to the brain. "Studies have shown that Staufen protein levels are markedly upregulated in multiple cell and animal models of human neurodegenerative diseases, including those associated with mutations in presenilin 1, and microtubule-associated protein tau, as well as in stroke and myotonic dystrophy." (PMID 33024434, 2020). "S100B, NSE, GFAP, and MAPT have previously been used as markers of neuronal damage, such as in stroke, traumatic brain injury, and aneurysmal SAH." (PMID 32978732, 2021). "Knockout of MAPT prevented brain damage in mice after MCAO-induced stroke." (PMID 36105479, 2022). "In recent years, MAPT has gained wide attention for its potential role in stroke." (PMID 36105479, 2022). "Some specific lysine residues in MAPT can be deacetylated by SIRT1, which means that a pivotal role is played by SIRT1/MAPT pathway during stroke recovery." (PMID 36105479, 2022). "However, there is no direct evidence to prove that the Sirt1/MAPT pathway plays a role in stroke directly through antioxidant responses." (PMID 36105479, 2022).
Anxiety (6 papers, 2018 to 2025). Intense feelings of nervousness, tension, or panic often arise in response to interpersonal stresses. "We compared MAPT KI to wild-type (WT) C57BL/6j mice in behavioral assessments of anxiety, attention, working memory, spatial memory, and motor performance from 6 to 24 months (m) of age." (PMID 37842124, 2023). "Patients with the MAPT gene variants were highly affected by anxiety, whereas hallucinations and delusions were virtually absent." (PMID 33404617, 2021).
autism (6 papers, 2019 to 2024). Persistent deficits in social interaction and communication and interaction as well as a markedly restricted repertoire of activity and interest as well as repetitive patterns of behavior. "Moreover, the MAPT gene is implicated in the mediation of autism-like behaviors by impairing myelination in oligodendrocytes and synaptic function in neurons." (PMID 40729198, 2023). "This interaction appears to mediate subsequent interactions with a network of other autism-related genes’ protein, including CYFIP1, MAPT, APBB1, SNAP25, and CDK16." (PMID 39376742, 2024).
epilepsy (6 papers, 2020 to 2025). A brain disorder characterized by episodes of abnormally increased neuronal discharge resulting in transient episodes of sensory or motor neurological dysfunction, or psychic dysfunction. "For APOE we additionally tested for association with hyperlipidaemia and for APP and MAPT we tested for associations with mental health and epilepsy." (PMID 41123760, 2025). "Proteomic data showed that total levels of APP and MAPT were unchanged in epilepsy." (PMID 38289539, 2024). "The most commonly observed disadvantageous alteration of MAPT in neurons is hyperphosphorylation, which occurs in many pathological conditions, including neurodegenerative disorders, traumatic brain injury, ischemia, epilepsy, and environmental stress." (PMID 33519375, 2020). "However we should note that because few participants had epilepsy the confidence intervals for this phenotype are large and, although we do not detect any effect, we cannot rule out the possibility that LOF variants in APP or MAPT might have a substantial effect on risk." (PMID 41123760, 2025).
glaucoma (6 papers, 2022 to 2024). Increased pressure in the eyeball due to obstruction of the outflow of aqueous humor. "MAPT (microtubule-associated protein tau) is associated with both the ganglion cell inner plexiform layer (GCIPL) and the retinal nerve fiber layer (RNFL), indicating that it might impact glaucoma pathogenesis through modulation of retinal thickness." (PMID 37239387, 2023).
glioblastoma (6 papers, 2014 to 2023). The most malignant astrocytic tumor (WHO grade IV). "Although direct links between MAPT and autophagy in cancer remain limited, the high expression levels of Tau protein in glioblastoma, a tumor with enhanced autophagy activity, have raised questions about its possible role in oncogenesis and its implications for cancer therapy." (PMID 37628602, 2023).
ischemia (6 papers, 2018 to 2024). A hypoperfusion of the BLOOD through an organ or tissue caused by a PATHOLOGIC CONSTRICTION or obstruction of its BLOOD VESSELS, or an absence of BLOOD CIRCULATION. "In CA3, fluctuations in MAPT gene expression were observed within control limits 2 days post-ischemia." (PMID 38542064, 2024). "Recent studies have documented an association between the expression of the tau protein (MAPT) gene in the CA1 and CA3 regions of the hippocampus after ischemia with a 30-day survival." (PMID 35052650, 2022). "In the CA1 area, the expression of the MAPT gen considerably increased on the second day after ischemia." (PMID 34571862, 2021). "They include alterations in amino acid sequences within the MAPT gene, altered transcription, multiple posttranslational influences (but especially hyperphosphorylation), head trauma, ischemia, and oxidative stress." (PMID 32775506, 2020). "Studies have shown opposite changes in MAPT gene expression in CA1 and CA3 areas 2, 7, and 30 days after ischemia." (PMID 38542064, 2024).
prion disease (6 papers, 2014 to 2023). A transmissible disease that is caused by a protein that is able to induce abnormal folding of normal cellular proteins, leading to characteristic spongiform brain changes, which are associated with neuronal loss without an inflammatory response. "These include amyloid-β (Aβ) and hyperphosphorylated microtubule-associated-protein tau (p.tau) in AD; α-synuclein in PD; and misfolded prion protein (PrP) in prion diseases." (PMID 29246602, 2017). "Microtubule-associated protein tau (or simply “tau”) has several variant forms; examined in this study was tau transcript variant 2 (tau-2, GenBank accession NM_005910), routinely used in our laboratory as a biomarker for prion disease diagnosis." (PMID 25011440, 2014).
Aphasia (5 papers, 2019 to 2025). An acquired language impairment of some or all of the abilities to produce or comprehend speech and to read or write. "Analogously, non-fluent aphasia phenotypes have been described with exon 10 MAPT mutations." (PMID 38592608, 2024). "In this context, the role of the MAPT missense mutation p.K298E has been up to now described only in a single clinical case report of a 67-year-old woman, who died at the age of 68, with rapidly progressive non-fluent aphasia associated with gait difficulties." (PMID 38592608, 2024). "On the other hand, potential risk mutations were found in patient #2, such as P513A in MAPT, which was suggested to play a role in progressive non-fluent aphasia, or TREM2 p.P211L, which may be a risk modifier for AD/FTD." (PMID 30917570, 2019). "MAPT p.P513A was first reported in a Chinese family with progressive non-fluent aphasia." (PMID 30917570, 2019).
Intellectual disability (5 papers, 2016 to 2025). "Many of these genes have been previously implicatedwith human phenotypes, including developmental delay (e.g. ASPM, AFF3 and MAPT) and intellectual disability (e.g. NEMF, PI4KA and KANSL1)." (PMID 31757203, 2019).
liver cancer (5 papers, 2020 to 2025). An epithelial or non-epithelial malignant neoplasm that arises from the liver. "In conclusion, this study elucidates the tumorigenic roles of PTBP1 and the MAPT-L isoform of MAPT in liver cancer cell migration, invasion, and metastasis." (PMID 40296916, 2025). "Therefore, MAPT, TOP2A, CENPF and MEFV were identified as hub genes of CTD targets that regulate autophagy and also sever as oncogenes or tumour suppressor genes to affect the prognosis of patients with liver cancer." (PMID 38017425, 2023).
primary progressive aphasia (5 papers, 2010 to 2024). Primary progressive aphasia (PPA) is a neurodegenerative disorder, characterized by a primary dissolution of language, with relative sparing of other mental faculties for at least the first 2 years of illness. "However, unlike MAPT mutations patients in this group frequently present with primary progressive aphasia (PPA) and GRN mutations are more likely to cause early parietal lobe impairment." (PMID 20045477, 2010).
asthma (4 papers, 2015 to 2026). "Of the lung function candidate genes, rare variant burden in four genes (MAPT, CFDP1, EML3, and LTBP4) was nominally associated with asthma risk in our study." (PMID 35368043, 2022). "Genes in this locus, which include MAPT and CRHR1, have previously been associated with pulmonary fibrosis and inhaled corticosteroid response in asthma." (PMID 26423011, 2015).
autoimmune disease (4 papers, 2019 to 2024). A disorder resulting from loss of function or tissue destruction of an organ or multiple organs, arising from humoral or cellular immune responses of the individual to their own tissue constituents. "Indeed, genetic variants within MAPT have been related to autoimmune diseases, normal lung function, and interstitial lung disease." (PMID 38605121, 2024). "Known for encoding the tau protein, traditionally associated with neurodegenerative disorders, recent studies have begun investigating MAPT’s role in autoimmune diseases." (PMID 38675400, 2024). "A resent genome-wide association study has identified several shared loci (including HLA-DRB5, LRRK2, and MAPT) between PD and 7 autoimmune diseases (including psoriasis, rheumatoid arthritis, and so on), suggesting that there were some common genetic risks between PD and autoimmune diseases." (PMID 31929812, 2019).
behavioral variant frontotemporal dementia (4 papers, 2016 to 2025). "Increased 18F-AV-1451 retention was noticed in bilateral temporal lobes in carriers of MAPT mutation, and frontotemporal binding was observed in 50% of the behavioral variant frontotemporal dementia (bvFTD) patients." (PMID 34458044, 2021). "Here, we compare the magnitude and distribution of [18F]AV‐1451 binding in healthy controls to a patient with behavioral variant frontotemporal dementia (bvFTD) resulting from a 10 + 16C>T mutation in the microtubule‐associated protein tau gene (MAPT)." (PMID 28097206, 2016).
Cerebral atrophy (4 papers, 2021 to 2025). Atrophy (wasting, decrease in size of cells or tissue) affecting the cerebrum. "Additionally, it is worth noting that GRN mutations are associated with a widespread pattern of cerebral atrophy, whereas MAPT mutations primarily result in atrophy in specific regions, such as the anteromedial temporal region." (PMID 37762113, 2023). "Two studies reported associations between circulating TNFα and increased cerebral atrophy, particularly in MAPT-FTD patients, but not in those with C9ORF72- or GRN-mediated FTD." (PMID 40305176, 2025).
colorectal cancer (4 papers, 2020 to 2023). A primary or metastatic malignant neoplasm that affects the colon or rectum. "Studies have also confirmed that MAPT is often methylated, and hypermethylation is associated with poor prognosis in patients with stage II colorectal cancer." (PMID 37316840, 2023). "In colorectal cancer, CpG island hypermethylation in MAPT is found in about a quarter of the samples in a cohort with hundred stage II patients, but it was absent in normal colorectal mucosa." (PMID 33207722, 2020). "The tumor types occurring in FTDP-17 families were variable (hematological, lung, breast, and colorectal cancers) suggesting that mutations in TAU, the protein encoded by the MAPT gene, may present predisposing oncogenic elements for genomic instability without tissue specificity." (PMID 33207722, 2020).
Down syndrome (4 papers, 2016 to 2022). "However, comparison of scattering from lesions in the Down syndrome case with the MAPT mutation case indicates significant differences in the structure of the cross-β core." (PMID 35720706, 2022). "Recently, IPSCs-derived astrocytes from Down syndrome (DS) patients were shown to be toxic to neurons but in this case astrocytes, like neurons, bear a trisomy of chromosome 21 whereas MAPT is located on chromosome 17." (PMID 29187256, 2017).
multiple system atrophy (4 papers, 2016 to 2025). Multiple system atrophy (MSA) is a neurodegenerative disorder characterized by autonomic failure (cardiovascular and/or urinary), parkinsonism, cerebellar impairment and corticospinal signs with a median survival of 6-9 years. "The genetic basis of Multiple System Atrophy involves a complex interplay of various genetic factors, prominently featuring the SNCA gene, LRRK2 mutations, GBA mutations, COQ2 expression alterations, and abnormalities in the MAPT gene." (PMID 40291849, 2025). "MAPT H1 and its sub haplotype H1c are reported to be associated with increased risk for certain age-related neurodegenerative diseases, including progressive supranuclear palsy (PSP), corticobasal degeneration (CBD), Multiple System Atrophy (MSA) and Parkinson’s disease (PD)." (PMID 27458716, 2016).